IL10 (interleukin 10)
Diseases named in the same sentence as IL10 in open-access papers (continued):
Sharing a sentence is not in itself a finding about the gene and the disease.
COVID-19 (continued). "In COVID-19 patients, cytokine storm leads to increased serum levels of interleukins, particularly IL-8 and IL-10." (PMID 37299555, 2023). "A study examined the immunological responses of 13 COVID-19 patients and observed that the illness has elevated cytokines proportion with IL-6, IL-10, and TNF-alpha, along with enhanced monocytes and neutrophil counts." (PMID 37754237, 2023). "We have shown that the serum level of IL-10 has a good predictive value of disease progression in COVID-19." (PMID 37283736, 2023). "Monocytes from HD + COVID-19 patients showed an enhanced capacity for pro-inflammatory cytokine production, with GM-CSF, IL-1β, IL-8, IL-10, CCL2 and CCL3 as the most increased cytokines compared with uninfected HD patients." (PMID 36675231, 2023). "Our findings confirm a defined cytokine signature in severe COVID-19 (with elevated IL-2, IL-6, TNFα, IL-1β and IL-10), and add further evidence to the role of IP-10, G-CSF and IL-33 in the cytokine milieu associated with severe COVID-19." (PMID 37063871, 2023). "Blood level of IL-10 is significantly increased in the first week following the symptoms’ onset in patients who developed severe COVID-19." (PMID 37359549, 2023). "In the context of COVID-19, alterations in IL-10+ and CD39+ Treg subpopulations or an imbalance between Tregs/Th17 can be associated with disease severity." (PMID 36969257, 2023). "Among critically ill patients with COVID-19, serum IL-6 and IL-10 levels are usually higher, while serum GM-CSF, TNF- α, IFN-γ, IL-2 and IL-8 serve as ancillary cytokines with clinical prognostic value in contrast to patients without critical disease." (PMID 37568402, 2023). "We found higher systemic values of Gal-3, IL-10 and proinflammatory cytokines in patients with critically COVID-19." (PMID 36702907, 2023). "Concerning the influence of TNF-α, we found higher values in the group with severe COVID-19 in terms of IgA, IL-10, IL-33, IL-28A and CD40L and lower values of IgM." (PMID 38137381, 2023). "Being both P2X7R and NLRP3 tightly associated to the release of inflammatory cytokines, a reasonable anticipation is that their blood levels in COVID-19 should parallel that of the cytokines typically overexpressed in this disease, e.g., IL-6 and IL-10." (PMID 37215142, 2023). "IL-6, TNFα, and IL-10 levels were highest in severe and critical COVID-19 patients, with comparable levels to non-COVID-19 critical patients." (PMID 36509969, 2023). "There have been reports of a link between SNPs in the IL10 gene and respiratory viral infectious diseases; this cytokine is thought to be a critical molecule in COVID-19 development." (PMID 36882862, 2023). "In particular, M2 macrophages from AOSD and COVID-19 patients treated with PD1 were able to increase the production of the anti-inflammatory cytokine IL-10 and to enhance homeostatic restoration through MIP-1β production from phagocytes." (PMID 37153620, 2023). "Observational studies showed elevated levels of different cytokines in COVID-19 patients, such as TNFα, IL-1β, IL-6, IL-8, IL-10, and IL-17." (PMID 36983830, 2023). "Several studies have also reported that circulating levels of IL-10 are significantly elevated in severe cases of COVID-19, especially in patients admitted to the ICU compared to those not requiring ICU care and continued to increase after admission." (PMID 37359549, 2023). "The top three biomarkers with the highest potential to differentiate between COVID-19 and the HCs were IL-10, IFN-α, and TNF-α." (PMID 38005844, 2023). "Inhibitors of janus kinase (JAK) block the intracellular signalling pathways of cytokines that promote and sustain inflammation in severe COVID-19, including IL-2, IL-6, IL-10, GM-CSF and IFNγ." (PMID 36941580, 2023). "Quantification of cytokines in the stool of patients hospitalized for COVID-19 revealed higher IL-8, IL-18, and lower IL-10 levels." (PMID 37006316, 2023).
COVID-19 (continued). "In addition, serum levels of both IL-6 and IL-10 correlated positively with pulmonary lesion volumes on chest CT scans caused by COVID-19, while others argued that the TNF-α/IL-10 ratio could readily estimate progression to acute respiratory failure during COVID-19." (PMID 37568402, 2023). "This is possibly the mechanism through which IL-10 is reduced in COVID-19 patients treated with Jusvinza." (PMID 37187739, 2023). "In men aged 35 years and older, we noted an increase in the proportion of sperm with fragmented DNA, higher concentrations of cytokines such as IL-1β and IL-10, and a decrease in the antioxidant defense of seminal plasma after COVID-19." (PMID 37958725, 2023). "SARS-CoV-2 infection triggers extensive production of pro-inflammatory molecules such as CRP, TNF-α, IL-1β, IL-6, MIP-1α, IP-10 and IL-10 by activated inflammatory monocytes and neutrophils recruited into the lungs of COVID-19 patients." (PMID 37854602, 2023). "This supports the idea that elevated levels of IL-10 in the post-COVID-19 period, allow a more efficient resolution of the immunopathological process, by improving anti-inflammatory response." (PMID 37359549, 2023). "COVID-19 severity is associated with CRS, with excessive elevation of IL-10 levels in critically ill patients." (PMID 37161468, 2023). "Although different cytokines have been found as deregulated in COVID-19 patients, IL-10, due to its multifaceted role in modulating inflammation, appears as one of the most intriguing." (PMID 37359549, 2023). "The levels of the inflammatory cytokines interleukin-6 (IL-6) and IL-10 appeared generally increased at diagnosis and decreased in post-COVID-19 patients." (PMID 37896963, 2023). "It is generally believed that the imbalance in Th1 and Th2 responses in COVID-19 patients triggers a cellular inflammatory storm, and increase the levels of inflammatory mediators such as interleukin IL-4, IL-10, and IL-6 in tissue samples." (PMID 37180704, 2023). "In patients with severe COVID-19, IL-10 was negatively correlated with vWF, which indicated endothelium dysfunction." (PMID 37814134, 2023). "In our study, the elevation of IL-6 and IL-10 was observed in newborns of mothers with COVID-19, who were born inflamed and possibly with a cytokine storm, as mentioned." (PMID 36979888, 2023). "Mainly, the MVPA covariate adjusted IL-10, triglycerides, and leptin in the plasma of post- COVID-19 patients." (PMID 37753077, 2023). "Next, we were interested in evaluating the effect of COVID-19 related medications on the blood levels of IL-35+IL-10+ Bregs as well as cTregs/uTregs subsets and LAG3+cTregs/uTregs." (PMID 37833265, 2023). "The protein–protein interaction network corresponding to these differentially expressed cytokines/chemokines identifies sIL2R->IL6->IP-10->IL-10->MIG as the network path with the highest inflammation in MIS-C relative to COVID-19." (PMID 37685502, 2023). "This study reports an increase in levels of both conventional and unconventional subtypes of Foxp3+ Tregs (cTregs/uTregs), as well as IL-35+ and IL-10+ producing Bregs, in the blood of COVID-19 patients during infection and relative to disease severity." (PMID 37833265, 2023). "Expression levels of IL-6, TNF-α, IFN-γ, IL-10, IL-12p70, IL-1β, IL-8, IL-13, IL-2, IL-7, IL-17A, IL-5 and IL-7 were measured in saliva and serum pairs obtained from the COVID-19 patients with available baseline symptoms information." (PMID 36846089, 2023). "So far, research has shown that COVID-19 patients with NAFLD have a distinct cytokine profile including increased levels of IL-6, IL-8, IL-10, and CXCL10, all associated with a more severe clinical presentation." (PMID 37375073, 2023). "This explanation is corroborated by the observations of severe COVID-19 in patients with type II diabetes, who were previously shown to have diminished IL-10 action due to hyperglycemia." (PMID 37371831, 2023).
COVID-19 (continued). "Alternative potential scenarios were proposed to explain the clinical meaning of the increase in IL-10 levels in serum of COVID-19 patients occurring within a few days from infection." (PMID 37359549, 2023). "Elevated levels of IL-8, IL-10, and IL-18 were found in pregnant women in their healthy state, and these cytokine levels remained elevated during acute and convalescent COVID-19." (PMID 37036008, 2023). "IL-10 was previously found to be elevated in COVID-19 patients and to be correlated with disease severity." (PMID 37600829, 2023). "The cytokine profile of the inflammatory cascade in SARS-CoV-2 was well defined, with concentrations of TNF-α, IL-6 and IL-10 distinctly mediating the cytokine storm and clearly differentiating mild from severe cases of COVID-19." (PMID 37759873, 2023). "On the other hand, critically ill COVID-19 patients display an increase of IL-10 related to a worsening of this disease." (PMID 37187739, 2023). "Similar to our study, non-survivor patients with COVID-19 infection had significantly higher IL-6 and IL-10 concentrations compared to survivor patients with COVID-19 on hospital admission." (PMID 36766961, 2023). "They found that compared with healthy patients, activated PBMCs from COVID-19 patients released fewer IL-10 and more IL-18." (PMID 37175774, 2023). "We validated previously published data that IL-8 chemokine and IL-6 and IL-10 cytokines were abundantly present in acute COVID-19 patients." (PMID 37228606, 2023). "Differences in IL-8, IL-10, and IL-18 levels were evident during healthy pregnancy, and these cytokines remained elevated during acute and convalescent COVID-19." (PMID 37036008, 2023). "Other studies revealed that elevated serum IL-10 levels in patients with COVID-19 can be both an anti-inflammatory mechanism and an immunosuppressive biomarker." (PMID 37969879, 2023). "The elevations of IL-10, IL-23, and TNF-α levels were seen in severe and critical cases of COVID-19 patients and their elevations were linked to the in-hospital mortality of the disease." (PMID 37283736, 2023). "The IL10 rs1800871 CC genotype, compared to other genotypes, was significantly related to COVID-19 mortality." (PMID 36882862, 2023). "The regulatory mechanisms of reduced mHLA-DR expression in severe/critical COVID-19 patients are less well understood, but IL-6 and IL-10 are similarly thought to be possible drivers to reduce mHLA-DR expression in the disease." (PMID 36834656, 2023). "The IL-10 case is intriguing as increase of this cytokine in COVID-19 is widely believed to be the result of a feed-back mechanism." (PMID 37215142, 2023). "These markers were associated with circulating indexes of respiratory disease severity (Horowitz index and alveolar-to-arterial oxygen gradient), inflammation (interleukin-6 and interleukin-10), and hypercoagulability (D-dimer) in COVID-19 patients with ARDS." (PMID 37408073, 2023). "The plasma levels of IL-6 and IL-10 (P<0.0001, respectively) were significantly increased in patients with COVID-19 as compared to the HC." (PMID 37207201, 2023). "Another clinical study also showed increased levels of IL-6 and IL-10 amongst 32 COVID-19 patients who are now deceased due to SARS-CoV-2 infection compared to those who survived." (PMID 37457959, 2023). "In one study of 52 individuals infected with COVID-19, the maximum concentrations of plasma cytokines (IL-2, IL-5, IL-17, IL-8, IL-10, IL-6, IL-12p70, and IFN-γ) were found to be significantly higher in those who had died than in those who had survived." (PMID 36766961, 2023). "Excessive, deleterious cytokine storms driven primarily by significant increases of IL-6/sIL-6R, IL-8, and IL-10 levels were also observed in severe COVID-19 patients compared with mild COVID-19 patients." (PMID 36851954, 2023).
COVID-19 (continued). "A study that analyzed cytokine levels in patients with COVID-19 found that the serum levels of IL-6, IL-8, and IL-10 were significantly higher in patients with a more severe form of the disease." (PMID 37969879, 2023). "For example, the concentrations of IL-6 and IL-10 were higher on day 7 in severe COVID-19 patients compared to concentrations measured at onset." (PMID 36851312, 2023). "ROC curve was used also to assess the accuracy of the association between the increase of serum IL-10 and TLR-4 and the presence of lymphopenia among COVID-19 patients." (PMID 36864077, 2023). "Among other inflammatory mediators, interleukin 10 (IL-10) has also been shown to be increased in COVID-19." (PMID 37008787, 2023). "In summary, we identified distinct Treg and Breg subtypes in COVID-19 patients, most notably IL-35+ and IL-10+ producing Bregs, which showed a correlation with disease severity and the presence of auto-Abs to type I IFNs." (PMID 37833265, 2023). "PBMCs from COVID-19 patients also showed upregulated IL-10 production, an anti-inflammatory cytokine that is correlated with disease severity." (PMID 36992700, 2023). "We recently showed that patients with NAFLD have higher levels of IL-6, IL-8, IL-10, and CXCL10, and lower levels of IFN-γ, and these were associated with worse COVID-19 outcomes." (PMID 37375073, 2023). "COVID-19 Patients with high IL-10, IL-23, and TNF-α on admission are more likely to experience a severe form of the disease; therefore, those patients should be cautionary monitored and treated." (PMID 37283736, 2023). "Analysis of cytokine at pretreatment showed that the COVID-19 positive patients had significantly elevated levels of IL-17A, IL-6, IL-10, MIG, MCP-1 and IP-10." (PMID 37662953, 2023). "The higher serum concentration of IL-10 in the severe and critical group of COVID-19 patients has been noticed in this study." (PMID 37283736, 2023). "In conclusion, our findings in COVID-19 patients show that increased blood levels of the sP2X7R very interestingly positively correlated with IL-10 and PCT, among the investigated inflammatory markers." (PMID 37215142, 2023). "Cytokine concentration (TNF-alfa, IFN-gamma, IL-2, IL-4, IL-6, and IL-10) increased greatly after in vitro exposure to the COVID-19 vaccine." (PMID 37686102, 2023). "In severe COVID-19 cases a drastic early rise in IL-10 was observed, an effect that represents a paradoxical role of this cytokine in its classical anti-inflammatory role." (PMID 37359549, 2023). "Multiple cases of acute pancreatitis in patients with COVID-19 have been reported in the literature and altered serum cytokine levels of increased IL-6, IL-8, and IL-10 were found to be similar in cases of severe acute pancreatitis and in cases of COVID-19." (PMID 36672197, 2023). "In fact, elevated levels of SM (24:1) were positively correlated with clinical and inflammatory indicators in COVID-19, including the clinical score, hospitalization days, and neutrophil count, as well as the production of IL-10, IL-6, and IL-8." (PMID 37566018, 2023). "Serum levels of IL-6, IL-8, and IL-10 were significantly increased in patients with COVID-19, but their predictive value regarding disease severity and the need for oxygen therapy was poor." (PMID 37969879, 2023). "IL-8, IL-10, and IL-18 were increased in healthy pregnant women and remained elevated during COVID-19." (PMID 37036008, 2023). "In patients admitted to medical emergencies with a confirmed diagnosis of COVID-19, it is important to perform a joint evaluation of demographic characteristics, clinical parameters, interleukins (IL-2, IL-6, IL-7, IL-10, IL-17) and sP-selectin." (PMID 36835858, 2023). "Available evidence has verified that COVID-19 patients had increased serum levels of proinflammatory cytokines, such as IL-1β, IL-6 and IL-10, alluding to the implication of a cytokine storm." (PMID 37251383, 2023).
COVID-19 (continued). "We have determined anti-inflammatory cytokine IL-10 levels on after COVID-19 primary and booster doses." (PMID 38173725, 2023). "Several studies showed a significant increase in inflammatory cytokines, such as IL-3, IL-6 and IL-10, among patients with a severe or lethal disease course of COVID-19." (PMID 36769623, 2023). "The levels of all analyzed interleukins, including TNF, IL-6, IL-1B, IL-8, IL-10, and IL-12p70, were significantly higher in the COVID-19 group compared to the control group." (PMID 37373613, 2023). "Consistent with previous reports, COVID-19 patients displayed higher levels of TNFα, IL-1β, IL-6, IFNα, IFNβ, TGFβ and IL-10 in comparison with HD." (PMID 37063865, 2023). "Elevated levels of IL-8, IL-10, and IL-18 were found in pregnant women in their healthy state, and these cytokine levels remained elevated during COVID-19." (PMID 37036008, 2023). "Increased serum levels of IL-10 has been previously demonstrated as a prognostic factor in COVID-19 patients." (PMID 37283736, 2023). "Volunteers who recovered from mild COVID-19 presented elevated levels of IL-10 producing Tregs, which points to a sustained immunosuppressive microenvironment that can attenuate inflammation upon reinfection." (PMID 36969257, 2023). "Owing to its anti-viral activity and anti-pro-inflammatory effects, in this review, IL-10 is suggested as a possible treatment agent for COVID-19." (PMID 36914565, 2023). "In COVID-19 patients, CRP has been already described as a bad outcome predictor, together with the cytokines associated with its expression (IL-6, IL-10)." (PMID 37373750, 2023). "Lastly, hyperinflammation during COVID-19 is probably accompanied by a simultaneous anti-inflammatory immune response driven by serum IL-10, which therefore also bears a deterministic effect on disease severity." (PMID 37568402, 2023). "Regarding the inflammatory response, TNF-α, IL-1β, IL-6, GM-CSF, IL-8, IL-4, and IL-10 are involved in BA to alleviate COVID-19, ALI, PF, COPD, PAH, and asthma." (PMID 37007037, 2023). "COVID-19 hyper-inflammatory subpopulation, compared to pauci-inflammatory, had higher levels of IL-10 (median [IQR] 61.4 [42.0–109.4] vs 13.0 [5.0–24.9], P: < 0.001), IL-6 (48.1 [22.3–82.6] vs 9.1 [0.1–30.4], P: < 0.001), among others." (PMID 36814234, 2023). "The clinical significance of highly elevated IL-10 amounts in the serum of COVID-19 patients has been generally regarded as an anti-inflammatory or immune-inhibitory mechanism." (PMID 36560410, 2022). "The results of the present study showed that in the plasma of COVID-19 patients, the expression of pro-inflammatory cytokines—TNFα and IL-6 and the anti-inflammatory interleukin—IL-10 increases, especially in the plasma of recovered COVID-19 patients." (PMID 36233111, 2022). "Emerging studies also reported that IL-10 is a well-known marker of COVID-19 severity in the clinical setting." (PMID 35903092, 2022). "A recent meta-analysis from 18 clinical studies identified IL-10 as a covariate that accurately predicted disease severity in COVID-19 patients." (PMID 37521849, 2022). "Although, cytokine storm in COVID-19 patients is similar to that previously seen in SARS patients infected by SARS-CoV, but a distinctive characteristic of COVID-19 cytokine storm is a drastic increase in interleukin 10 (IL-10) serum levels in severe patients." (PMID 37521849, 2022). "We found that while many cytokines, including IL-6, showed an impact on the prognosis of COVID-19 patients, only two of them, IL-1RA and IL-10, were of clinical significance in the subgroup of patients receiving tocilizumab therapy." (PMID 35887283, 2022). "The patients of the second wave showed lower levels of iNOS, IL-6, and IL-10, as compared to the corresponding subgroup of the first wave, suggesting a less severe outcome of COVID-19 in these patients." (PMID 35336941, 2022).